RNF149 (ring finger protein 149)
Description:
E3 ubiquitin-protein ligase. Ubiquitinates BRAF, inducing its proteasomal degradation.
Synonyms: DNAPTP2; FLJ90504
Tractability: Antibody: UniProt predicts a signal peptide or a membrane-spanning region; the Human Protein Atlas places it where antibodies can reach. PROTAC: ubiquitination databases record sites on it.
Gene: Protein-coding gene on chromosome 2 (101,271,219 to 101,308,724, reverse strand). Ensembl gene ENSG00000163162.
Subcellular location: Membrane
Subcellular location (Human Protein Atlas): Plasma membrane; Vesicles
Gene Ontology:
Molecular function: ubiquitin protein ligase activity
Biological process: ubiquitin-dependent protein catabolic process; protein ubiquitination
Cellular component: membrane; endoplasmic reticulum; Golgi apparatus; late endosome
Genetic constraint (gnomAD): Loss-of-function variants: 12 observed, 26.48 expected, observed/expected ratio (o/e) 0.45, 90% interval 0.29 to 0.73. The upper end of that interval is the gene's LOEUF score, 0.73, which puts it in group 3 of 6, group 1 being the genes least tolerant of losing a copy. Missense variants: 392 observed, 433.8 expected, observed/expected ratio (o/e) 0.9, 90% interval 0.83 to 0.98. Synonymous variants: 185 observed, 184.15 expected, observed/expected ratio (o/e) 1, 90% interval 0.89 to 1.13.
Homologues: Orthologues: chimpanzee RNF149 (99% identical), macaque RNF149 (93% identical), dog RNF149 (84% identical), pig RNF149 (79% identical), mouse Rnf149 (77% identical), rat Rnf149 (76% identical), tropical clawed frog rnf149 (59% identical), guinea pig RNF149 (50% identical). Paralogues in human: RNF150 (40% identical), RNF130 (38% identical), RNF128 (35% identical), RNF148 (28% identical), RNF133 (27% identical), RNF13 (19% identical), RNF167 (18% identical), ZNRF4 (17% identical), RNF215 (16% identical).
Diseases named in the same sentence as RNF149 in open-access papers:
RNF149 is named in the same sentence as 22 diseases in open-access papers, as found by Europe PMC text mining. Sharing a sentence is not in itself a finding about the gene and the disease. The quoted sentences say what the papers report.
colorectal cancer (2 papers, 2023 to 2025). A primary or metastatic malignant neoplasm that affects the colon or rectum. "It has been previously reported that RNF149 gene is mutated in some human cancers, including breast, ovarian, and colorectal cancer." (PMID 37958377, 2023). "Various studies have reported that RNF149 played a role in tumors, such as colorectal cancer, nasopharyngeal cancer, hepatocellular carcinoma and esophageal squamous cancer." (PMID 40245000, 2025). "It has been reported that RNF149 promotes cell survival in colorectal cancer and inhibits cell migration in NPC." (PMID 37958377, 2023). "In colorectal cancer, RNF149 selectively degrades wild-type B-RAF instead of mutant B-RAF." (PMID 37958377, 2023). "As an E3 ubiquitin ligase, only two experimentally validated substrates of RNF149 were reported so far: wild-type but not mutant BRAF in colorectal cancer, and EPHA2 in NPC." (PMID 37958377, 2023).
esophageal squamous cell carcinoma (2 papers, 2024 to 2025). Esophageal squamous cell carcinoma (ESCC) is a type of esophageal carcinoma (EC) that can affect any part of the esophagus, but is usually located in the upper or middle third. "Moreover, RNF149 confers cisplatin resistance in esophageal squamous cell carcinoma through PHLPP2 ubiquitination." (PMID 41000374, 2025).
hepatocellular carcinoma (2 papers, 2023 to 2025). A malignant tumor that arises from hepatocytes. "The latest research shows that RNF149 can accelerate the progression of hepatocellular carcinoma by ubiquitinating the substrate DnaJ homolog subfamily C member 25 (DNAJC25)." (PMID 40245000, 2025). "In this study, based on proteomics data analysis, really interesting new gene (RING) finger protein 149 (RNF149) was found to be elevated in hepatocellular carcinoma (HCC) tissues and associated with HCC malignancy, which was validated by immunohistochemistry (IHC) staining." (PMID 37958377, 2023).
nasopharyngeal carcinoma (2 papers, 2023 to 2025). A carcinoma arising from the nasopharyngeal epithelium. "In nasopharyngeal carcinoma (NPC), MFSD4A-recruited RNF149 mediates the ubiquitination and degradation of EPHA2, thus inhibiting the proliferation, migration, and invasion of NPC cells." (PMID 37958377, 2023).
prostate carcinoma (2 papers, 2022). A carcinoma that arises from epithelial cells of the prostate gland. "On the other end, a recent study searching germline modifier genes possibly associated with aggressive prostate cancer, by GWAS and human prostate tumor expression data set analyses, identified RNF149 among four genes that could contribute to disease aggressiveness in PC patients." (PMID 35634494, 2022). "RNF149, demonstrated as a DEG between normal tissue and prostate cancer, was discovered to be associated with 2[18F]fluoro-2-deoxy-d-glucose (FDG) uptake during positron emission tomography (PET) and survival in non-small cell lung cancer patients." (PMID 35831825, 2022).
acute myeloid leukemia (1 paper, 2023). Acute myeloid leukemia (AML) is a group of neoplasms arising from precursor cells committed to the myeloid cell-line differentiation. "In conclusion, RNF149 is implicated in fostering drug resistance in acute myeloid leukemia by both enhancing the proliferation of resistant cells and reducing their sensitivity to cytarabine." (PMID 37891580, 2023). "Through integrating scRNA-seq and Bulk-seq databases, we discerned a notably overexpressed E3 ligase, RNF149, in acute myeloid leukemia (AML), which correlates with survival outcomes." (PMID 37891580, 2023).
Alzheimer disease (1 paper, 2025). A progressive, neurodegenerative disease characterized by loss of function and death of nerve cells in several areas of the brain leading to loss of cognitive function such as memory and language. "In Alzheimer’s disease, the knockdown of RNF149 can ameliorate the symptoms of the disease." (PMID 40245000, 2025). "In addition to its role in tumors, RNF149 also has a regulatory effect in Alzheimer’s disease." (PMID 40245000, 2025).
atherosclerosis (1 paper, 2023). A disease characterized by the build-up of fatty material and calcium deposition in the arterial wall resulting in partial or complete occlusion of the arterial lumen. "In our results in TAO (a vascular disease that involves medium and small vessels without atherosclerosis and causes narrowing and occlusions as a result of the inflammation of arteries and veins) patients, we detected an increase in RNF149 expression." (PMID 38275601, 2023).
colon adenocarcinoma (1 paper, 2024). "In the ERK1/2 signaling pathway, E3 ligases RNF149 and FBXW7 regulate the stability of B-Raf in colon adenocarcinoma (COAD), leading to its degradation." (PMID 39048965, 2024).
colon cancer (1 paper, 2022). "A study carried in human colon cancer and embryonic kidney cell lines reported that RNF149 indirectly regulated cell differentiation by reducing BRAF, a kinase known for its pro-proliferation function." (PMID 35634494, 2022).
myeloproliferative neoplasm (1 paper, 2023). A clonal hematopoietic stem cell disorder, characterized by proliferation in the bone marrow of one or more of the myeloid (i.e., granulocytic, erythroid, megakaryocytic, and mast cell) lineages. "Impairment in RNF149 function increases translocation flux into the ER and manifests in a myeloproliferative neoplasm (MPN) phenotype, a pathological condition associated with pEQC impairment." (PMID 37031316, 2023).
pancreatic cancer (1 paper, 2024). "Ring Finger Protein 149 (RNF149) regulates ubiquitination and proteasomal degradation and is associated with pancreatic cancer." (PMID 38673800, 2024).
viral infection (1 paper, 2025). "Similarly, we found that RNF149’s effects on viral infection are linked to the type I IFN signaling pathway through MEF cells." (PMID 40245000, 2025). "It’s indicated that the regulation of viral infection by RNF149 is associated with IFN-I signaling." (PMID 40245000, 2025). "Western blot and plaque assay both confirmed the function of RNF149 overexpression on viral infection." (PMID 40245000, 2025). "Next, we further verified the regulation of RNF149 on viral infection in primary mouse peritoneal macrophages." (PMID 40245000, 2025). "The results showed that overexpression of RNF149 led to lower levels of IFN-β mRNA compared to the control group with virus infection." (PMID 40245000, 2025). "The results showed that, after RNF149 knockdown, cells produced higher levels of Cxcl10 and Mx1 following viral infection." (PMID 40245000, 2025). "The results demonstrated that knocking down of RNF149 reduced viral infection, as shown by decreased GFP and mCherry signals." (PMID 40245000, 2025). "Herein, we revealed the regulatory role of RNF149 in the host's innate immune responses against viral infection." (PMID 40245000, 2025). "The immunofluorescence assay showed that overexpression of RNF149 promoted viral infection, as shown by increased GFP and mCherry signals." (PMID 40245000, 2025). "Our study has unveiled a novel role for RNF149 in the innate immune response against viral infection, thus offering a new strategy for the treatment of RSV infection." (PMID 40245000, 2025). "Herein, we found the regulatory role of RNF149 in the host's innate immune responses against viral infection." (PMID 40245000, 2025). "In this study, we identified RNF149 as a negative regulator in the host's immune response to viral infection." (PMID 40245000, 2025). "In conclusion, we have clarified that RNF149 expression is induced upon viral infection, and RNF149 regulates the IRF3 degradation." (PMID 40245000, 2025). "Upon viral infection, RNF149 expression was induced, facilitating viral replication possibly via suppressing the production of IFN-β." (PMID 40245000, 2025). "Our findings highlight the negative regulatory role of RNF149 in viral infection and provide new insights into how host cells respond to such infection." (PMID 40245000, 2025). "Our results revealed the regulatory mechanism of RNF149 during viral infection and provided new insights into host cells responding to viral infection." (PMID 40245000, 2025). "The RT-qPCR results showed that the upregulation of RNF149 expression induced by viral infection was suppressed in the IFNAR1 antibody-blocking group." (PMID 40245000, 2025). "The RT-qPCR and Western blot results showed that the expression of RNF149 in macrophages increased after virus infection." (PMID 40245000, 2025). "The effects of RNF149 on viral infection depend on the E3 ubiquitin ligase activity." (PMID 40245000, 2025). "Downregulating the expression of RNF149 may help enhance the antiviral ability of host cells and inhibit viral replication, thus providing a new strategy for the treatment of viral infection." (PMID 40245000, 2025). "Conversely, RNF149 knockdown promoted the IFN-β expression after virus infection." (PMID 40245000, 2025). "Additionally, we confirmed the effect of RNF149 knockdown on virus infection by Western blot and plaque assay." (PMID 40245000, 2025). "We also verified the impact of RNF149 on virus infection by overexpression in HEK293T cells." (PMID 40245000, 2025). "The results showed that knockdown of RNF149 reduced viral infection in Ifnar1+/+ cells." (PMID 40245000, 2025). "To explore whether the upregulation of RNF149 expression following viral infection is regulated by the downstream signaling pathway of Type I interferon, we stimulated RAW264.7 cells with a gradient of different concentrations of IFN-β." (PMID 40245000, 2025).
viral infection (continued). "Taken together, we demonstrate that RNF149 limits IFN-β production during viral infection and negatively regulates innate antiviral responses." (PMID 40245000, 2025). "However, the knockdown of RNF149 did not affect viral infection in Ifnar1−/− MEF cells." (PMID 40245000, 2025).
tumor (7 papers, 2014 to 2024). "To investigate the association between RNF149 and the tumor microenvironment (TME) of AML, we employed cibersortX, utilizing annotated scRNA data to examine the cellular components within the AML bone marrow microenvironment." (PMID 37891580, 2023). "Additionally, they highlighted the association between elevated RNF149 expression and an immunosuppressive tumor microenvironment." (PMID 39104473, 2024). "Thus, our results supported the notion that high RNF149 levels were associated with immunosuppressive tumor microenvironment." (PMID 37958377, 2023). "GO analysis indicated a primary enrichment in tumor microenvironment and immune regulatory functions, hinting at RNF149’s role in immune system activation and regulation." (PMID 37891580, 2023). "Consistent with the protein level results, RNF149 mRNA was significantly upregulated in tumor tissues and highly expressed in S-III subtypes of HCC." (PMID 37958377, 2023). "To verify our results from omics data, we conducted IHC staining experiments to determine the RNF149 expression in an independent HCC cohort using the tumor tissue microarray." (PMID 37958377, 2023). "Conversely, the RNF149-shRNA group demonstrated a significant decline in tumor volume relative to the shRNA-NC group." (PMID 37891580, 2023). "Immunofluorescence studies indicated diminished green fluorescence intensity in the tumor tissues of the shRNA-RNF149 mice, reflecting a reduced expression of the RNF149 protein when contrasted with the NC-shRNA group." (PMID 37891580, 2023). "According to our data, RNF149 was significantly upregulated in tumor tissues, and its expression increased profoundly along with the rising malignancy of three subtypes of HCC." (PMID 37958377, 2023). "In this study, based on our previous proteomics data, we found that RNF149 was upregulated in tumor tissues and correlated with poor diagnosis of HCC patients." (PMID 37958377, 2023). "b Flank xenograft tumor growth over time using lentiviral ectopic over-expression of candidate genes RNF149 and STYXL1 in the LNCaP PC cell line." (PMID 29890952, 2018). "c Flank xenograft final tumor weight after 5 weeks using lentiviral ectopic over-expression of candidate genes RNF149 and STYXL1 in the LNCaP PC cell line." (PMID 29890952, 2018). "The expression of Peroxiredoxin 4 (PRDX4) was up in 28 (87.5 %) tumors and increased 1.92-fold on average, while RNF149 was overexpressed approximately 2.26-fold in one tumor specimen." (PMID 24318988, 2014). "As RNF149 is an E3 ubiquitin ligase, we further investigated whether its ligase activity was required for its tumor-promoting functions." (PMID 37958377, 2023). "RNF149 was demonstrated to promote proliferation, migration, and invasion of HCC cells dependent on its E3 ubiquitin ligase activity in vitro, and further bioinformatics analysis indicated that high expression of RNF149 correlated with immunosuppressive tumor microenvironment (TME)." (PMID 37958377, 2023). "In this study, based on the proteomic profiling data of paired early-stage HCC samples, we found that RNF149 was strikingly upregulated in tumor tissues and correlated with poor prognosis in HCC patients, which was further validated by IHC staining experiments of an independent HCC cohort." (PMID 37958377, 2023). "Furthermore, in the subcutaneous tumor formation assay, RNF149-overexpressing Huh7 cells exhibited a significantly increased tumor size and weight of cells compared with the control group." (PMID 37958377, 2023). "GSEA analysis suggested that RNF149 high-expression cells might activate certain signaling pathways, potentially influencing tumor progression and immune responses." (PMID 37891580, 2023). "In addition, bioinformatics analysis showed that high expression of RNF149 was correlated with immunosuppressive tumor microenvironment (TME), indicating its potential role in immune regulation of HCC." (PMID 37958377, 2023).
tumor (continued). "Our in vitro and in vivo assessments revealed that RNF149 impedes apoptosis in AML cells, augments their proliferation, and mirrors this function in drug-resistant AML subsets and murine tumor models." (PMID 37891580, 2023). "The tumor immune microenvironment (TIME) plays a significant role in response to immunotherapy, and according to the previous analysis results, the RNF149-high group had significantly enriched immune response pathways." (PMID 37958377, 2023). "In our research, we proved that RNF149 promoted cell growth and migration of HCC cells, and these tumor-promoting effects were dependent on its E3 ubiquitin ligase activity." (PMID 37958377, 2023). "DNAJC10, RNF149 and STYXL1 all harbored significantly higher mRNA expression levels in tumor tissues compared to normal prostate." (PMID 29890952, 2018). "None of the other genes DNAJC10, RNF149 or STYXL1 had a significant effect on tumor growth or tumor weight." (PMID 29890952, 2018). "On the other hand, we did not observe any expression changes in the RNF149 gene (when SNORD89 showed down-regulation in tumor tissues relative to normal tissues)." (PMID 27631501, 2016).
cancer (2 papers, 2022 to 2023). A tumor composed of atypical neoplastic, often pleomorphic cells that invade other tissues. "However, one cannot exclude that it may correspond to a true RNF149 variant mRNA with intron retention, as found for a number of germ cell and cancer variant transcripts." (PMID 35634494, 2022). "Based on TCGA data, RNF149 expression was also significant in many other cancers, including HCC and breast cancer." (PMID 37958377, 2023). "Therefore, RNF149 might be a potential prognostic marker and drug target for HCC treatment, and more efforts are required to clarify its cellular functions and molecular mechanisms in cancers for better clinical translation." (PMID 37958377, 2023).
infection (1 paper, 2025). The state of being infected such as from the introduction of a foreign agent such as serum, vaccine, antigenic substance or organism. "RNF149 knockdown in RAW264.7 cells increased the production of Ifnb with the infection of both SeV and HSV-1." (PMID 40245000, 2025).
RNF149 also shares sentences with these, for which no sentence is quoted: breast carcinoma (1 paper); Moyamoya disease (1); non-small cell lung carcinoma (1); prostate adenocarcinoma (1); prostate tumor (1); teratoma (1).